ADAM17 (ADAM metallopeptidase domain 17)
Diseases named in the same sentence as ADAM17 in open-access papers (continued):
Sharing a sentence is not in itself a finding about the gene and the disease.
heart failure (10 papers, 2012 to 2023). Inability of the heart to pump blood at an adequate rate to meet tissue metabolic requirements. "It was also found that over-activated renin–angiotensin system (RAS) can enhance ACE2 shedding and subsequently the up-regulation of ADAM-17 (increase in ADAM-17 activity due to the ROS-induced phosphorylation) induces heart failure, acute coronary disease due to the loss of ACE2." (PMID 33442728, 2021). "Cleavage of membrane ACE2 by up-regulated proteases in advanced heart failure, such as tumor necrosis factor-∝ ADAM17 may deplete local myocardial ACE2 causing LV remodeling." (PMID 23630610, 2013). "The increased expression of ADAM17, TNFα, and sIL-6R has a vital implication in aggravating cardiac dysfunction during heart failure development." (PMID 34966735, 2021). "In contrast, in the kidney ADAM17 expression/abundance was decreased in correlation with the heart failure severity." (PMID 33660945, 2021). "This comprehensive review provides an insight into the structure of ADAM17, how it is activated and regulated during chronic catecholamine stress in heart failure development." (PMID 34966735, 2021). "Animal studies demonstrated that ADAM17 promoted the occurrence of post-MI HF, as indicated by increased infarct size, cardiomyocyte hypertrophy, myocardial interstitial collagen deposition and cardiac failure." (PMID 37046278, 2023). "Furthermore, we confirmed much higher levels of ADAM17 expression in early peripheral blood of patients with heart failure after MI, suggesting an early warning role for ADAM17, but larger data are still needed." (PMID 37046278, 2023). "Hence, this concise review provides a comprehensive insight into the structure of ADAM17, how it is activated and regulated during chronic catecholamine stress in heart failure development." (PMID 34966735, 2021). "However, there is limited information on the cardiovascular aspect of ADAM17, especially in heart failure." (PMID 34966735, 2021). "Cellular retention of ACE2 is therefore required for its role as a cellular anchor and, as such, the cleavage of ACE2 by ADAM17 may be a pathological step in the development of heart failure." (PMID 22523556, 2012). "Thus, establishing a positive correlation between ADAM17 and heart failure development." (PMID 34966735, 2021). "Our studies show that inhibition of ADAM17 expression reduced the shedding of ACE2, which in turn protected against adverse cardiac remodeling and the progression of heart failure." (PMID 37046278, 2023). "Overexpression and chronic activation of ADAM17 can trigger excessive release of TNFα, sIL-6R, and CXCR2 on the surface of proinflammatory cells, which play crucial roles in the pathogeneses of several inflammatory diseases, including heart failure." (PMID 34966735, 2021). "Mechanistically, activated ADAM17 inhibited the cardioprotective effects of ACE2 by promoting hydrolytic shedding of the transmembrane protein ACE2 in cardiomyocytes, which subsequently mediated the occurrence of cardiac remodeling and the progression of heart failure." (PMID 37046278, 2023).
lung adenocarcinoma (10 papers, 2016 to 2025). A carcinoma that arises from the lung and is characterized by the presence of malignant glandular epithelial cells. "Beyond COVID‐19, reduced ADAM17 expression in lung may have promising implications in KRAS mutation‐driven lung adenocarcinoma." (PMID 38886986, 2024). "Here, we investigated ADAM17 and IR-mediated migration of tumor cells using the lung adenocarcinoma cell line NCI-H358." (PMID 36998455, 2023). "Our data show, that both, basal and IR-induced cancer cell migration of the lung adenocarcinoma cell line NCI-H358 was reduced towards CM derived from ADAM17 knockdown cells." (PMID 36998455, 2023). "Overall, we here successfully demonstrate the efficacy of the combined treatment modality of radiotherapy with the novel ADAM17-directed inhibitory antibody MEDI3622 for lung adenocarcinoma." (PMID 36860547, 2021). "As part of an extended screening approach, we previously identified IR-dependent upregulation of ADAM17 sheddase activity and secretion of angiogenic factors from lung adenocarcinoma cells." (PMID 36860547, 2021). "Then, the antiviral properties of the three ADAM17 inhibitors were assayed on SARS-CoV-2-infected human lung adenocarcinoma Calu-3 cells after cytotoxicity evaluation with the aim to prove their efficacy to impair the alternative entry pathway of SARS-CoV-2 in host cells." (PMID 39292373, 2025). "Our study focused on the expression level of ADAM17 and ADAM10 in lung adenocarcinoma related specimens and the expression level of miRNA acting on ADAM10, and finally found that miR-140-3p in lung adenocarcinoma tissues has more clinical significance compared with other miRNAs." (PMID 36606198, 2022).
Cognitive impairment (9 papers, 2011 to 2025). Abnormal cognition is characterized by deficits in thinking, reasoning, or remembering. "It identifies mechanistic connections through which ADAM17 and associated pathways may influence the emergence of mild cognitive impairment." (PMID 38963109, 2024). "Additionally, reduced ADAM17 function has been linked to Aβ accumulation, short-term memory, and cognitive deficits in mice." (PMID 38963109, 2024). "This study aims to analyse the relationship of ADAM17/TACE gene polymorphism with the risk, age of onset, neuropsychiatric manifestations, cognitive impairment, and medial temporal lobe atrophy in sporadic AD (sAD)." (PMID 40327644, 2025). "In this study, we set out to examine the role of ADAM17 in contributing to vascular and cognitive impairments by using an established mouse model of AD, the APP/PS1 mice." (PMID 36937050, 2023). "We found that 9-10 months old APP/PS1 mice with b-amyloid accumulation and short-term memory and cognitive deficits display a markedly reduced expression of ADAM17 in cerebral microvessels." (PMID 36937050, 2023). "Thus, targeting ADAM17 represents a promising approach for treating cognitive impairment and neurodegenerative diseases." (PMID 38963109, 2024). "Patients with cognitive deficits show increased plasma ADAM17 activity." (PMID 37095509, 2023). "However, the role of ADAM17 in the development of cerebrovascular and cognitive impairments in AD remains incompletely understood." (PMID 36937050, 2023).
neuroblastoma (9 papers, 2013 to 2025). Neuroblastoma (NB) is the most common solid, extracranial childhood tumor. "To analyze possible effects of the mutation on ADAM17 biochemical function, we generated neuroblastoma (SH-SY5Y) cell lines stably over-expressing the newly identified variant of ADAM17 (p.R215I)." (PMID 29988083, 2020). "It ameliorated Aβ (1-40 and 1-42) production by activating α-secretase TACE (tumour necrosis factor-α-converting enzyme or disintegrin and metalloproteinase-17 or ADAM17) in cultured SH-SY5Y human neuroblastoma cells." (PMID 36831081, 2023).
chronic kidney disease (8 papers, 2012 to 2023). Impairment of the renal function secondary to chronic kidney damage persisting for three or more months. "The disintegrin and metalloenzyme ADAM17 participates in numerous inflammatory and proliferative diseases, and its pathophysiological role was implicated in kidney fibrosis, polycystic kidney disease and other chronic kidney diseases." (PMID 22413019, 2012). "For instance, patients with chronic kidney disease have increased plasma levels of sMer and sAxl with increased expression of ADAM17 on monocytes." (PMID 32964059, 2020). "Elevated plasma concentrations of tumor necrosis factor receptor 1 (TNFR1) and tumor necrosis factor receptor 2 (TNFR2), two ADAM17 substrates, have been recently found to predict stage 3 chronic kidney disease (CKD) and ESRD in patients with type 1 and type 2 diabetes, respectively." (PMID 33634991, 2021). "Our data suggest that regulating α5β1 integrin binding to ADAM17 could be an attractive therapeutic target in chronic kidney diseases." (PMID 22413019, 2012). "We suggest that regulating α5β1 integrin binding to ADAM17 could be an attractive therapeutic target in chronic kidney diseases." (PMID 22413019, 2012). "TIMP3 is a known physiological inhibitor of ADAM17, a metalloprotease responsible for shedding of several ligands; among these, HB-EGF and TGF-β are involved in the pathogenesis of chronic kidney disease and glomerulonephritis." (PMID 34181080, 2021). "Moreover, TIMP3 is the only known physiological inhibitor of ADAM17, a metalloprotease responsible for shedding of several ligands, in particular HB-EGF and TGFα, which are involved in the pathogenesis of chronic kidney disease and glomerulonephritis." (PMID 23401241, 2013).
inflammatory bowel disease (8 papers, 2013 to 2025). A spectrum of small and large bowel inflammatory diseases of unknown etiology. "Indeed, knock-in mice with 95% decreased levels of TACE/ADAM17 showed increased susceptibility to inflammatory bowel disease, which again is critical for medical treatment." (PMID 23757215, 2013). "ADAM17 recombinant pro-domain has been shown to specifically inhibit ADAM17 in different mouse models and might enter into clinical development for the treatment of inflammatory bowel disease." (PMID 32698506, 2020). "Also, there is evidence that targeting ADAM17 for inflammatory diseases such as inflammatory bowel disease (IBD) would be successful." (PMID 29230082, 2017). "Inhibition of ADAM17 may have deleterious consequences for long-term administration, as it played a protective role in the intestinal mucosa in a mouse model of inflammatory bowel disease." (PMID 29230082, 2017). "Also, recently, an inhibitor of ADAM17 based on its prodomain may be entering into the clinic for inflammatory conditions such as inflammatory bowel disease (IBD)." (PMID 29230082, 2017). "In addition, recently, an inhibitor of ADAM17 based on its pro-domain entered the clinic for inflammatory conditions such as inflammatory bowel disease (IBD)." (PMID 39768182, 2024). "Both of these receptors were found in blood serum and up-regulated along with ADAM17, known to affect L-selectin (CD62) shedding, with ADAM17, a TNF-α convertase, also upregulated in inflammatory bowel disease (IBD)." (PMID 36851285, 2023).
lymph node metastasis (8 papers, 2011 to 2022). "ADAM17 expression is associated with poor survival (HR = 2.04, 95% CI = 1.66–2.52, p < 0.001), lymph node metastasis (OR = 5.47, 95% CI = 3.98–7.51, p < 0.001) and distant metastasis (OR = 3.50, 95% CI = 1.79–6.87, p < 0.001) in many types of tumors." (PMID 34943606, 2021). "ADAM17 is associated with an advanced TNM stage and the presence of lymph node metastasis and is a significant biomarker for poor prognosis in GC." (PMID 35565436, 2022). "The meta-analysis revealed that lower ADAM17 levels were correlated with longer overall survival rates in GC, while ADAM17 overexpression was associated with an advanced TNM stage and the presence of lymph node metastasis." (PMID 35565436, 2022). "Our study shows that lower ADAM17 levels are correlated to the longer OS time in GC and ADAM17 was associated with TNM stage, lymph node metastasis, and age." (PMID 32610677, 2020). "The percentage of positive ADAM17 protein expression in the lymph node metastasis group was significantly higher than that of the lymph node-negative group (P<0.05)." (PMID 25351873, 2015). "ADAM17 mRNA expression in esophageal squamous cell carcinoma was correlated with lymph node metastasis (P<0.01) and tumor, node and metastasis (TNM) staging (P<0.05), however, it was not correlated with gender, age or histological grade (P>0.05)." (PMID 25351873, 2015). "Therefore, based on meta-analyses data, there is an association of increased ADAM17 expression in a number of tumor types, including GC, with the poor OS, TNM stage and lymph node metastasis." (PMID 34943606, 2021). "The elevated expression of ADAM17 was significantly associated with such characteristics as higher TNM stage (OR = 4.09, 95% CI 1.85–9.04; I2 = 84.1%; p = 0.000), lymph node metastasis (OR = 3.08, 95% CI 1.13–8.36; I2 = 79.7%; p = 0.007), and age (OR = 1.65, 95% CI 1.24–2.21; I2 = 0%; p = 0.692)." (PMID 32610677, 2020). "The multivariate Cox proportional hazards model analysis showed that ADAM17, EGFR, lymph node metastasis and TNM stage all had independent prognostic significance (all P<0.05)." (PMID 25351873, 2015). "High ADAM17 expression was also related to the tumor node metastasis (TNM) stages (OR = 4.09, 95% CI 1.85–9.04; I2 = 84.1%; p = 0.000), lymph node metastasis (OR = 3.08, 95% CI 1.13–8.36; I2 = 79.7%; p = 0.007), and ages (OR = 1.65, 95% CI 1.24–2.21; I2 = 0%; p = 0.692) of the gastric patients." (PMID 32610677, 2020). "In our study, we found that ADAM17 was association with TNM stage, lymph node metastasis, and age but not tumor differentiation and sex." (PMID 32610677, 2020). "In addition, ADAM17 protein expression in esophageal squamous cells was correlated with lymph node metastasis and TNM stage (P<0.05), while it was not correlated with gender, age or histological grade (P>0.05)." (PMID 25351873, 2015).
oral cancer (8 papers, 2012 to 2023). "In a second step, we examined the effect of ADAM17 overexpression in SCC-9 cells in events associated with oral cancer development." (PMID 24495306, 2014). "The understanding of the mechanism by which ADAM17 is associated with oral cancer progression will provide the basis for the development of novel and refined OSCC-targeting approaches." (PMID 24495306, 2014). "In summary, our study shows that ADAM17 overexpression interferes in the biological processes associated with oral tumorigenesis and it is able to promote an increase tumor size and proliferation in an orthotopic murine model for oral cancer development." (PMID 24495306, 2014). "Taken together, our findings indicate potential proteins regulated by ADAM17 overexpression and demonstrate the potential role of ADAM17 in the development of oral cancer." (PMID 24495306, 2014). "In this report we have provided novel evidences demonstrating ADAM17 overexpression has a potential role in oral cancer development." (PMID 24495306, 2014). "Firstly, we demonstrated, in an orthotopic tumor model for oral cancer, that tumors overexpressing ADAM17 presented an increase in size and showed higher proliferative activity by immunohistochemical expression of Ki-67 (respectively)." (PMID 24495306, 2014). "Furthermore, stable suppression of ADAM17 in HNSCC cells also diminished tumorigenesis in an oral cancer mouse model." (PMID 24403253, 2013). "Thus, targeting the cleavage of HB-EGF by ADAM17 may be effective in overcoming chemotherapy resistance in oral cancer." (PMID 22209887, 2012). "Although some studies have also shown an important role of ADAM17 in head and neck cancer, none of them investigated the ADAM17-mediated signaling components that might be involved in oral cancer development." (PMID 24495306, 2014). "Then, despite the close relationship between ADAM17 and EGFR, it is still not clear the role that ADAM17 plays in oral cancer development." (PMID 24495306, 2014).
renal carcinoma (8 papers, 2013 to 2025). A carcinoma arising from the epithelium of the renal parenchyma or the renal pelvis. "In kidney cancer cell lines, LPA-induced HB-EGF shedding and subsequent EGFR transactivation is mediated by ADAM10 in ACHN cells, whereas ADAM17 is responsible for these events in human renal carcinoma cells (CaKi2) and Human kidney carcinoma cell line (A498)." (PMID 25356505, 2014). "Through immunohistochemical staining assay we found that ADAM-17 was highly expressed in renal carcinoma tissues." (PMID 23659326, 2013). "Compared with γ-secretase, inhibition of ADAM-17 expression more effectively inhibits Notch pathway-mediated renal cancer cell proliferation and invasion." (PMID 23659326, 2013). "Immunohistochemistry and western blot were used to examine the expression of ADAM-17 protein in renal cancer tissues." (PMID 23659326, 2013). "Our study is to research the effect of inhibited ADAM-17 expression through the Notch pathway in renal carcinoma." (PMID 23659326, 2013). "In our research, we demonstrate that high expression of ADAM-17 is closely related to the malignancy of renal cancer." (PMID 23659326, 2013). "ADAM-17 which is the key enzyme has been reported to be highly-expressed in renal carcinoma in the mRNA level in 27 patient samples." (PMID 23659326, 2013). "ADAM17 is overexpressed in various cancer types, including renal cancer." (PMID 40689207, 2025). "However, in this study, 67 renal carcinoma tissues were examined and found to express high levels of ADAM-17 in different TNM stages, especially the advanced stages, T3 and T4." (PMID 23659326, 2013). "ADAM-17 may be a new target for future treatment of renal carcinoma." (PMID 23659326, 2013). "It has been demonstrated that miR-145 downregulates ADAM17 protein expression by directly targeting the 3′untranslated region (3′UTR) of ADAM17 mRNA, thereby reducing the proliferation and invasion of renal cancer cells." (PMID 40689207, 2025). "In normal PTE cells, MUC1, ADAM10 and ADAM17 proteins were undetectable whereas all of them were expressed in RCC4, RCC10 and 786-O renal cancer cell lines." (PMID 24504508, 2014). "In contrast, MUC1, ADAM10 and ADAM17 were absent in PTE cells while they were expressed in renal cancer cell lines." (PMID 24504508, 2014). "In renal carcinoma context, studies have reported (i) an increased expression of ADAM10 and ADAM17 in renal cancer tissues and cell lines and (ii) that renal cancer cells failed to develop tumours in vivo in the absence of ADAM17." (PMID 24504508, 2014). "Moreover, A disintegrin and metalloproteinase domain-containing protein 17 (ADAM17) can be directly targeted by miR-145, which initiates a negative feedback loop involving the ADAM17 substrate TNF-α, which is upregulated and subsequently reduces miR-145 expression in renal carcinoma cell lines." (PMID 30081513, 2018).
renal fibrosis (8 papers, 2014 to 2025). A final common manifestation of a wide variety of chronic kidney diseases characterized by glomerulosclerosis and tubulointerstitial fibrosis. "In tethered cells, high glucose levels increase the expression of HIF‐1α and its target gene ADAM17, thereby accelerating renal fibrosis." (PMID 40977522, 2025). "To gain an insight into the role of Adam17 deletion on renal fibrosis, we examined cortical α-SMA expression and collagen depositions in the studied groups." (PMID 34073747, 2021). "Adam17 knockout (Adam17KO) mice presented reduced renal fibrosis and inflammation after acute kidney injury (AKI) induction or angiotensin II (ANG II) infusion." (PMID 34073747, 2021). "It has been reported that an ADAM17 inhibitor was effective in reducing renal fibrosis in angiotensinII-induced kidney disease in mice." (PMID 25285155, 2014). "Another study has also indicated that ADAM17-mediated production of soluble heparin binding epidermal growth factor (HB-EGF) is also involved in renal fibrosis via activation of EGF receptor (EGFR) signaling." (PMID 25285155, 2014). "Inhibition of ADAM17 reduced renal fibrosis in mice with Ang II-induced kidney disease." (PMID 40224489, 2025). "Previous studies have shown that inhibition of ADAM17 reduces renal fibrosis in angiotensin II-induced kidney disease in mice, suggesting that ADAM17 and its action to cleave ACE2 may play an important role in kidney disease." (PMID 25786223, 2015). "Additionally, ADAM17 cleaves cell membrane IL‐6R, releasing soluble IL‐6R, which binds to IL‐6 forming complexes that act on gp130 protein on immune cell membranes, activating the intracellular JAK/STAT pathway to induce renal fibrosis." (PMID 40077919, 2025).